EREG (epiregulin)
Diseases named in the same sentence as EREG in open-access papers (continued):
Sharing a sentence is not in itself a finding about the gene and the disease.
cancer (continued). "However, these gain-of-functions effects were almost completely depleted by EREG-specific shRNAs, which retained normal proliferative potential of stromal cells but reversed the malignant phenotypes of recipient cancer cells." (PMID 36202915, 2022). "Moreover, a comprehensive understanding of pathways obtained through multiomic analyses may clarify the detailed characteristics of TMEs and the spatial compartmentalization of EREG/EGFR signaling and crucial related molecules, thus providing new insights into treatment against cancer development." (PMID 34884633, 2021). "Interestingly, in non-basal and TKI resistant cancer cells (J82), inhibition of EGFR phosphorylation mediated by erlotinib was associated with increased mRNA expression of EGFR (FC: 44.6), ERBB3 (FC: 92.3) and EREG (FC: 3.5)." (PMID 32978523, 2020). "Cancer cells with low expression of AREG and EREG may possibly indicated that it not sensitive to anti-EGFR therapies." (PMID 34884633, 2021). "However, EREG overexpression in stromal cells failed to confer survival advantage when these cells per se were treated with increasing concentrations of genotoxic chemicals such as BLEO, implying different survival mechanisms between cancer and stromal cells." (PMID 36202915, 2022).
infection (9 papers, 2016 to 2025). The state of being infected such as from the introduction of a foreign agent such as serum, vaccine, antigenic substance or organism. "Here we found that genes IRS2, NRG1, HBEGF, and EREG regulating AKT signaling are downregulated in M-MDSC isolated from CoV2+ participants long after recovery from infection." (PMID 35812392, 2022). "Our quantitative PCR data showed that three ligands, HB-EGF, AREG and EREG, displayed significant up-regulation at 60 min after infection with strain RS218, while the transcriptional levels of EGF, BTC and TGFα remained unchanged during the infection." (PMID 27711202, 2016). "EREG acts as an epidermal growth factor receptor ligand that exhibits a regulatory property by inhibiting the growth of epithelial cells as well as regulating inflammation and the immune response during infection." (PMID 30634928, 2019). "Since activation of the EGF receptor is important for H. pylori-induced gastrin promoter activation, the absolute levels of mRNA expression were next determined for the EGF family members (HB-EGF, AR, EGF, TGF-α, BTC, epigen, and epiregulin) using qRT-PCR at 1, 2.5, and 5 h post-infection." (PMID 29379775, 2017). "Module 2 focused on epithelial barrier function and growth factor signaling, identified EREG, FGFR2, and MET as central hubs, alongside AREG and HBEGF, which support epithelial repair and regeneration after infection-induced damage." (PMID 40634947, 2025). "Epiregulin (EREG) belongs to the epidermal growth factor (EGF) family, which binds to the epidermal growth factor receptor (EGFR) to regulate the immune response of the host during infections." (PMID 30634928, 2019). "More importantly, the quantitative real-time PCR data supported that viable SC19 infection of hBMEC could stimulate the upregulation of AREG, EREG, and HB-EGF, while the heat-inactivated SC19 was unable to upregulate these ligands." (PMID 27756321, 2016). "The results showed that the triple deletion mutant was able to induce significant up-regulation of AREG and EREG after 60 min, while there was no up-regulation of HB-EGF, as well as EGF, BTC, and TGFα, after infection with the triple deletion mutant." (PMID 27711202, 2016).
intestinal diseases (1 paper, 2022). "Up-regulated EREG, SPP1, and PTGS2 by CotG-p40 support the claim that it can protect intestinal epithelial cells from intestinal diseases." (PMID 36550414, 2022).
skin disorder (1 paper, 2025). Any deviation from the normal structure or function of the skin or subcutaneous tissue that is manifested by a characteristic set of symptoms and signs. "Several studies indicated that abnormal changes in keratinocytes are associated with various skin disorders, and EREG plays a role in keratinocyte proliferation and differentiation." (PMID 41175573, 2025).
EREG also shares sentences with these, for which no sentence is quoted: colon adenocarcinoma (3 papers); myxoma (2); thoracic aortic aneurysm (2); acute lymphoblastic leukemia (1); adenocarcinoma (1); adrenocortical carcinoma (1); Alzheimer disease (1); anaplastic astrocytoma (1); Angiofibroma (1); aortic aneurysm (1); astrocytoma (1); bacterial infection (1); bladder urothelial carcinoma (1); breast (1); cholangiocarcinoma (1); chronic bronchitis (1); colon (1); colonic adenoma (1); colorectal adenocarcinoma (1); dissection (1); epilepsy (1); Follicular Cyst (1); gallbladder cancer (1); gastric tumor (1); gastrointestinal disease (1); glomerulonephritis (1); gynecological cancer (1); gynecological tumors (1); hypopharynx cancer (1); ichthyosis (1).
A further 21 diseases each share a sentence with EREG in 1 paper.